PGR (progesterone receptor)
Diseases named in the same sentence as PGR in open-access papers (continued):
Sharing a sentence is not in itself a finding about the gene and the disease.
Miscarriage (3 papers, 2018 to 2025). A pregnancy that ends at a stage in which the fetus is incapable of surviving on its own, defined as the spontaneous loss of a fetus before the 22th week of pregnancy. "TLR2, TLR4, IL-6, IL-8, and PGR SNPs were identified as secondary factors that can also affect the risk of miscarriage." (PMID 30116270, 2018). "TLR2, TLR4, IL-6, IL-8, and PGR SNPs can also affect the risk of miscarriage, but in less extent than TLR9 and IL-10." (PMID 30116270, 2018). "Thus, a complex study encompassing effects of major SNPs of cytokine, TLR, and PGR genes on the risk of miscarriage is needed." (PMID 30116270, 2018). "Inflammatory stimuli also seem to alter progesterone receptor activation; hence, transrepressive activity in myometrial cells, providing support for the hypothesis that tissue inflammation, may be involved in miscarriage and preterm delivery." (PMID 29861738, 2018). "When missed miscarriage is diagnosed and luteal support is withdrawn, the abrupt and complete withdrawal of estradiol and progesterone may synergize with the progesterone receptor blockade of mifepristone, accelerating endometrial breakdown and uterine evacuation." (PMID 40944098, 2025).
mucoepidermoid carcinoma (3 papers, 2016 to 2025). A carcinoma morphologically characterized the presence of cuboidal mucous cells, goblet-like mucous cells, squamoid cells, cystic changes, and a fibrotic stromal formation. "The mucoepidermoid carcinoma of the breast was weakly estrogen receptor and androgen receptor positive and progesterone receptor negative, but exceptionally showed human epidermal growth factor receptor 2 gene amplification." (PMID 38062474, 2023).
pancreatic neuroendocrine tumor (3 papers, 2011 to 2024). Pancreatic endocrine tumor, also known as pancreatic neuroendocrine tumor (PNET), describes a group of endocrine tumors originating in the pancreas that are usually indolent and benign, but may have the potential to be malignant. "Specifically, pancreatic NETs with better outcomes had higher estrogen receptor-β expression, while the loss of progesterone receptor expression was associated with higher grade, larger tumours, and decreased patient survival time." (PMID 39001438, 2024). "The loss of progesterone receptor (PR) expression was also observed in pancreatic neuroendocrine tumor (PanNET) patients with shorter survival time." (PMID 30547767, 2018). "It has been reported that normal pancreatic islet cells and pancreatic neuroendocrine tumors showed positive reactivity for the progesterone receptor, and our literature survey demonstrated that epithelioid cells showed a high positive rate for PP (89.7%, 70/78) immunohistochemically." (PMID 21599949, 2011).
preeclampsia (3 papers, 2023 to 2024). Preeclampsia is a hypertensive disorder of pregnancy that is characterized by new-onset hypertension with proteinuria presenting after 20 weeks of gestation, and depending on mild or severe forms may initially present with severe headache, visual disturbances, and hyperreflexia. "Alternatively, dysregulated PGR expression was related to severe preeclampsia and predisposition to RPL." (PMID 38195505, 2024). "Accordingly, placental estrogen and progesterone receptor dysregulations have been speculated to contribute to preeclampsia." (PMID 38534461, 2024). "Hence, our findings with the BPH/5 mouse may offer valuable insights into estrogen and progesterone receptor dysregulations during timepoints that are particularly challenging to investigate in human pregnancies affected by preeclampsia." (PMID 38534461, 2024). "Using a spontaneous model of superimposed preeclampsia, the Blood Pressure High Subline 5 (BPH/5) mouse, we tested the hypothesis that uteroplacental estrogen and progesterone receptor misexpression occur prior to pregnancy and during the peri-implantation period of preeclamptic-like pregnancies." (PMID 38534461, 2024).
pyometra (3 papers, 2013 to 2022). "Aglepristone is a progesterone receptor blocker and its use proved to be effective for the medical treatment of pyometra in bitches and queens." (PMID 36288130, 2022). "In dogs, aglepristone (RU534), a progesterone receptor antagonist, has been successfully used to terminate pregnancy in bitches and treat pyometra, vaginal tumors and mammary hyperplasia." (PMID 33670676, 2021).
renal carcinoma (3 papers, 2015 to 2020). A carcinoma arising from the epithelium of the renal parenchyma or the renal pelvis. "It is widely accepted that some renal cancers express ER and PGR." (PMID 26704433, 2015).
squamous cell carcinoma (3 papers, 2017 to 2025). A carcinoma arising from squamous epithelial cells. "Both the diseases usually lack expression of ER, PgR, and HER2, and GATA3 may be expressed in both MBC and squamous cell carcinomas." (PMID 40230815, 2025).
viral infection (3 papers, 2017 to 2022). "Viral infection also caused aberrant expression of estrogen and progesterone receptor in the cervical epithelium." (PMID 29190738, 2017). "Firstly, either PGR- or SRC-deficiency impaired progesterone-triggered potentiation of IRF3 activation and antiviral gene expression following viral infection." (PMID 35468896, 2022). "4-OH-TAM also down-regulated a number of genes, including PGR, S100A8, S100A9, CCND1 and ANEXA1, which are involved in IFN α/β signaling pathway and immune/inflammatory response to viral infection." (PMID 29416786, 2018).
B-cell lymphoma (2 papers, 2016 to 2025). "In this case, we present our experience treating a patient with synchronous stage IAE non-Hodgkin low-grade B-cell lymphoma, of marginal zone origin, and stage IA (pT1a, pN0, cM0, G1, estrogen receptor (ER)+, progesterone receptor (PR)-, HER2-) ILC, both located within the right breast." (PMID 40525019, 2025).
breast fibroadenoma (2 papers, 2017 to 2025). "Complete surgical excision was performed, and histopathological evaluation—including immunohistochemistry for estrogen receptor, progesterone receptor, GATA3, and p63—confirmed ectopic breast fibroadenoma." (PMID 41040519, 2025).
cervical tumor (2 papers, 2015 to 2016). "Pathology indicated that the cervical tumor was a poorly-differentiated adenocarcinoma, which was carcinoembryonic antigen (CEA) (-), vimentin (+), estrogen receptor (ER) (1+), and progesterone receptor (PR) (3+)." (PMID 25588929, 2015). "The WDEA components of both endometrial and cervical tumors were positive for ER and PgR, and negative for CD10, CD56, CEA, and p16." (PMID 26830028, 2016).
cognitive deficit (2 papers, 2013 to 2021). "Since TBI induces behavioral and cognitive deficit, in the present study, the efficacies of P4 on behavioral and cognitive parameters after TBI were investigated in the presence of classic progesterone receptor antagonist." (PMID 33995946, 2021).
colorectal tumor (2 papers, 2013 to 2025). "Immunohistochemical staining should be performed to check for estrogen and progesterone receptor expression, which are usually negative in primary gastro‐colorectal tumors." (PMID 40936680, 2025).
dementia (2 papers, 2021 to 2022). Loss of intellectual abilities interfering with an individual's social and occupational functions. "PGR and ADCY1 have been associated with neurodevelopment, but a direct link with dementia or neurodegeneration has not been found." (PMID 36389068, 2022).
endometrioid ovarian carcinoma (2 papers, 2019 to 2020). "Both ERα and progesterone receptor (PR) expression were strongly associated with improved survival for endometrioid ovarian carcinoma, while PR (but not ERα) was associated with favorable outcomes in HGSOC." (PMID 32580290, 2020).
fibrosis (2 papers, 2021 to 2025). the formation of excess fibrous connective tissue in an organ or tissue in a reparative or reactive process. "In this study, we found that P4/PGR signaling in a unique population of LAM fibroblasts plays a central role in LAM fibrosis and that pharmacologic inhibition of P4/PGR signaling prevents hernia development and stops hernia enlargement." (PMID 40504614, 2025).
gallstones (2 papers, 2012 to 2013). Solid crystalline precipitates in the biliary tract, usually formed in the gallbladder, resulting in the condition of cholelithiasis. "However, Alu insertion polymorphism of progesterone receptors (PGR) conferred lower risk with gallstones." (PMID 23577061, 2013). "In contrast, Alu insertion polymorphism of progesterone receptors (PGR) conferred lower risk in GBC and gallstone patients." (PMID 22808109, 2012). "For progesterone receptor polymorphism, very little is known about the functional consequences by which Alu insertion in progesterone receptor protect individuals from gallbladder carcinoma and gallstones." (PMID 22808109, 2012). "Therefore, in the present study, we investigated a panel of 6 well-studied polymorphisms in ESR1, ESR2 and PGR genes in a case–control design involving 410 GBC patients, 230 gallstone patients and 220 cancer/gallstone-free controls from North India." (PMID 22808109, 2012). "However, the variant-containing genotypes (DI+II) of PGR (rs1042838) showed low risk in both GBC [OR = 0.4] and gallstone patients [OR = 0.4].On performing the MDR analysis, ESR1 IVS1-397C>T, ESR1 IVS1-351A>G, and ESR2-789 A>C yielded the highest testing accuracy of 0.634." (PMID 22808109, 2012). "In case of PGR ins/del (rs1042838), a protective effect was observed in GBC patients irrespective of their gallstone status." (PMID 22808109, 2012).
hidradenocarcinoma (2 papers, 2015 to 2023). A carcinoma with apocrine and less often eccrine differentiation, arising from the sweat glands. "Another tumor that stood out after consultation was a clear cell hidradenocarcinoma mimicking the immunohistochemistry of a metastatic lobular carcinoma by presenting a positive estrogen receptor, a progesterone receptor, mammaglobin, and CK7 cytokeratin." (PMID 37958380, 2023). "On immunohistochemistry, hidradenocarcinomas are variably positive for androgen receptor (AR), estrogen receptor (ER), progesterone receptor (PR), EGFR (epidermal growth factor receptor), and HER-2 (human epidermal growth factor receptor 2)." (PMID 25815059, 2015).
lipoma (2 papers, 2025). A benign, usually painless, well-circumscribed lipomatous tumor composed of adipose tissue. "Similarly, a missense mutation in the PGR gene was observed exclusively in a benign tumor, namely, a lipoma." (PMID 41168812, 2025).
lung adenocarcinoma (2 papers, 2010 to 2016). A carcinoma that arises from the lung and is characterized by the presence of malignant glandular epithelial cells. "Overall survival was significantly better in ERα and in PgR positive lung adenocarcinoma patients (median survival 45 vs. 19 months)." (PMID 27690341, 2016). "To date, E2 has been shown to regulate the PGR gene in a sex-dependent fashion in specific brain regions of adult rats and in human lung adenocarcinoma cell lines." (PMID 21208464, 2010). "OS was significantly better in ER expressed vs. ER negative and in PgR exhibited vs PgR negative lung adenocarcinoma patients (median survival=45 months vs. 19 months in both groups, HR=0.38 [95% confidence interval (CI)=0.16-0.93], p=0.03 and HR=0.42 [95% CI=0.15-0.92], p= 0.04, respectively)." (PMID 27690341, 2016).
lymph node disease (2 papers, 2023 to 2024). "The variant allele showed significant associations with various tumor characteristics, including estrogen receptor (ER) and progesterone receptor (PR) status, the presence of lymph node disease, and tumor grade." (PMID 38610928, 2024). "Pre-therapy clinical N stage > 0, positive pre-therapy lymph node biopsy, estrogen and progesterone receptor positivity, Ki67 < 50%, HR + /HER2− tumors, and residual breast disease had higher likelihood of residual lymph node disease after NAC (p < 0.001)." (PMID 37286892, 2023).
lymphoma (2 papers, 2019 to 2023). A malignant (clonal) proliferation of B- lymphocytes or T- lymphocytes which involves the lymph nodes, bone marrow and/or extranodal sites. "Neither ERα on lymphoma cells nor PgR on FDCs and lymphoma cells was found in FL of any grade." (PMID 30736096, 2019).
male breast carcinoma (2 papers, 2014 to 2022). A malignant neoplasm involving the male breast. "Male breast cancer is often characterized by the expression of hormone receptors; specifically, over 90% of all cases are ER‐positive and over 80% are PGR‐positive." (PMID 35252796, 2022). "Male breast cancer has also been shown to have a higher frequency of hormone receptor (HR), estrogen receptor (ER) and progesterone receptor (PR), expression (80–90%) compared to females (75%)." (PMID 23755153, 2014).
mesothelioma (2 papers, 2024 to 2025). A usually malignant and aggressive neoplasm of the mesothelium which is often associated with exposure to asbestos. "A meta‐analysis has further revealed that the APC gene is significantly hypomethylated in mesothelioma, while CDH1, ESR1, miR‐34b/c, PGR, RARβ, SFRP1, and WIF1 are significantly hypermethylated." (PMID 40904706, 2025). "A recent systematic review and quantitative meta-analysis of DNA methylation in mesothelioma found both significantly hypomethylated genes (APC) and hypermethylated genes (CDH1, ESR1, miR34b/c, PGR, RATO, SFRP1, and WIF1)." (PMID 38297314, 2024).
multiple sclerosis (2 papers, 2013 to 2025). A progressive autoimmune disorder affecting the central nervous system resulting in demyelination. "Segesterone acetate (SA) is a selective and potent progesterone receptor agonist with potential application in the treatment of neurological diseases, such as multiple sclerosis and stroke." (PMID 40531370, 2025). "Although no studies have demonstrated an effect of PROG on Tau expression in glial cells, elevated PROG during pregnancy is thought to mediate remission of symptoms in women with multiple sclerosis via its effect on glial cells, which express the progesterone receptor." (PMID 23798570, 2013).
myoma (2 papers, 2014 to 2018). "In myomas of small and large size, in women at the reproductive age, high expression of progesterone receptor was detected involving, respectively, 95% and 75% of myoma cells." (PMID 25050358, 2014).
neuroendocrine neoplasm (2 papers, 2018 to 2022). Endocrine tumors, also referred to as neuroendocrine tumors (NETs), are defined by a common phenotype which is characterized by the expression of general markers (neuron specific enolase, chromogranin, synaptophysin) and hormone secretion products. "Furthermore, immunohistochemical expression of progesterone receptor and pancreatic polypeptide were useful in distinguishing between GP and neuroendocrine tumor G1, even in small biopsy specimens." (PMID 30101131, 2018).
Oral squamous cell carcinoma (2 papers, 2016 to 2022). "SIN, squamous intraepithelial neoplasia; OSCC, oral squamous cell carcinoma; ERα, Estrogen Receptor alpha; PR, Progesterone Receptor." (PMID 27475696, 2016). "Key words:Oral squamous cell carcinoma, estrogen receptor, progesterone receptor, hormone receptor." (PMID 27475696, 2016).
osteoporosis (2 papers, 2021 to 2024). A condition of reduced bone mass, with decreased cortical thickness and a decrease in the number and size of the trabeculae of cancellous bone (but normal chemical composition), resulting in increased fracture incidence. "However, selective progesterone receptor modulators (SPRMs) and pure progesterone receptor antagonists (PAs) can lead to severe estrogen deficiency, further contributing to vaginal atrophy, osteoporosis, and cardiovascular side effects." (PMID 39768606, 2024).
osteosarcoma (2 papers, 2022 to 2025). A usually aggressive malignant bone-forming mesenchymal neoplasm, predominantly affecting adolescents and young adults. "About 34% of cases exhibit mixed osteolytic and osteoblastic features, requiring differentiation from osteosarcoma (marked by a 5-fold elevation in alkaline phosphatase) and metastatic breast cancer (estrogen receptor/progesterone receptor positivity)." (PMID 41458551, 2025). "Estrogen receptors (ER-∝, ER-β), progesterone receptor (PR), and androgen receptor (AR), have been previously identified on human osteosarcoma (OSA) cells, and are considered to influence tumor growth, but their expression and role in canine OSA is unknown." (PMID 36288137, 2022).
Ovarian cyst (2 papers, 2023). The presence of one or more cysts of the ovary. "Interestingly, we showed a parallel drop in PGR mRNA and protein abundance in early atretic-like preovulatory follicles, which are precursors of ovarian cysts." (PMID 37173342, 2023).
ovarian serous cystadenocarcinoma (2 papers, 2019 to 2021). A malignant serous cystic epithelial neoplasm arising from the ovary. "Association among ERa, ERb, and PGR protein expression levels in tumor tissues of patients with ovarian serous cystadenocarcinoma and uterine endometrioid adenocarcinoma." (PMID 34322374, 2021). "Association of ERa, ERb, and PGR protein expression levels in tumors with the clinicopathological characteristics of patients with ovarian serous cystadenocarcinoma." (PMID 34322374, 2021). "The expression levels of ERa, ERb, and PGR proteins were detected by immunohistochemical staining using paraffin-embedded tissue specimens of ovarian serous cystadenocarcinoma (OV) and uterine endometrioid adenocarcinoma (UTEA)." (PMID 34322374, 2021). "MME, SOX17, AGTR1, PGR, and ESR1 had the highest amplifications frequency ranging from 4% to 11% in ovarian serous cystadenocarcinoma." (PMID 31879572, 2019).
pneumothorax (2 papers, 2021 to 2024). Abnormal presence of air in the pleural cavity. "The presence of estrogen- and progesterone-receptor-positive cells in the lung and diaphragm strongly suggests a hormonal influence on pneumothorax recurrence." (PMID 39664286, 2024). "Except for CP, lung resections for various types of pneumothorax demonstrated negative staining (0/50) with CD10 and hormonal receptors, estrogen receptor (ER) and progesterone receptor (PR)." (PMID 33477657, 2021).
prostate adenocarcinoma (2 papers, 2016 to 2021). "In addition, a low expression of PGR mRNA was found in CESC, colon adenocarcinoma (COAD), OV, prostate adenocarcinoma (PRAD), rectal adenocarcinoma (READ), TGCT, UCEC, and UCS samples." (PMID 34322374, 2021).
sarcoma (2 papers, 2013). A usually aggressive malignant neoplasm of the soft tissue or bone. "The strong and moderate (score 3 and 2, respectively) hormone receptor expression occurred mostly in sarcomas of uterus, pelvis and breast, while the weak (score 1) expression of both ER and PGR was surprisingly evenly distributed among location, gender and age." (PMID 23497154, 2013).
schizophrenia (2 papers, 2016 to 2024). A major psychotic disorder characterized by abnormalities in the perception or expression of reality. "Given the role of estrogen in the treatment of schizophrenia, we also examined sex hormone-related expression (AR, ESR1, ESR2, and PGR) in the brain." (PMID 38730231, 2024). "Notably, hypomethylation at 2 bp upstream of its TSS was reported in diseases such as estrogen and progesterone receptor-negative breast cancers, schizophrenia, and bipolar disorder." (PMID 27681076, 2016). "Here, we did not observe any sex-specific or sex-specific schizophrenia DEGs for sex hormone expression (AR [androgen receptor], ESR1 [estrogen receptor 1], ESR2 [estrogen receptor 2], and PGR [progesterone receptor]) across the brain." (PMID 38730231, 2024).
serous ovarian tumors (2 papers, 2022 to 2023). "Notably, the level of PGR mRNA showed a significant correlation with the level of PGR protein, both of which were significantly and inversely correlated with the level of CA125 in the blood serum of patients with serous ovarian tumors." (PMID 37569592, 2023).
smooth muscle tumor (2 papers, 2012 to 2017). A benign or malignant myomatous neoplasm arising from smooth muscle. "However PgR expression has been variably described in other prostatic mesenchymal neoplasms including smooth muscle tumours and SFT." (PMID 28687087, 2017).